HIF1A (hypoxia inducible factor 1 subunit alpha)
Diseases named in the same sentence as HIF1A in open-access papers (continued):
Sharing a sentence is not in itself a finding about the gene and the disease.
Sepsis (continued). "Furthermore, inoculation of live or heat-inactive gram-positive bacteria into macrophages induced HIF-1α, while mice deficient in myeloid HIF-1, were shown to be protected against gram-positive endotoxin-induced sepsis mortality and clinical symptomology." (PMID 31555665, 2019). "The current study aimed to investigate whether miR-31 has effects on intestinal barrier dysfunction by targeting HMOX1 through the NF-κB/HIF-1α pathway in sepsis." (PMID 30340459, 2018). "From all above, it can be hypothesized that the miR-31, HMOX1, and the HIF-1α/NF-κB pathway exert certain effects on sepsis." (PMID 30340459, 2018). "Given that EDA has been used clinically to treat ischemic stroke, the advancing knowledge we have provided here on the cardiac preconditioning effect of EDA via HIF-1α/HO-1 activation in sepsis may support a novel use of EDA as a treatment for septic patients." (PMID 29765498, 2018). "Compared with the sepsis group, the expression of NF-κB and HIF-1α mRNA and protein in ileal tissues were found to be significantly increased, while IκB, ZO-1 and Occludin mRNA and protein were significantly decreased in the miR-31 mimic group and the siRNA-HMOX1 group (all p < 0.05)." (PMID 30340459, 2018). "Previously, we have reported the expression of HIF1α in circulating monocytes during sepsis." (PMID 30233593, 2018). "We have previously reported that HIF1α played a crucial role in the reprogramming of monocytes toward an alternative phenotype during sepsis and that restoring adequate oxygenation reverts the tumor-promoting phenotype of OSA monocytes, reducing HIF1α expression, and subsequently VEGF secretion." (PMID 29997451, 2018). "There was a relationship between sepsis and viral infection, and HIF-1α and VEGF." (PMID 29026849, 2017). "In this study, we aimed to demonstrate whether VEGF-A and HIF-1α was correlated with pathogenesis of sepsis in serum samples obtained from CCHF patients and control group." (PMID 29026849, 2017). "We identified regulatory genetic variants involving key mediators of gene networks implicated in the hypoxic response and the switch to glycolysis that occurs in sepsis, including HIF1α and mTOR, and mediators of endotoxin tolerance, T-cell activation, and viral defence." (PMID 26917434, 2016). "The role of HIF-1α in inflammation has been examined in animal models of sepsis, rheumatoid arthritis and chronic cutaneous inflammation using conditional gene targeting approaches allowing tissue-specific deletion of HIF-1α and VHL." (PMID 26213713, 2015). "In addition, HIF-1α has been shown to play an essential role in the development of LPS-induced sepsis in mice, so that targeted deletion of HIF-1α has a protective effect." (PMID 23984430, 2013). "For example, T cells from HIF1α-deficient mice released significantly more tumor necrosis factor and IFN-γ after T cell receptor activation than wildtype T cells and mice showed an enhanced survival rate in a sepsis model." (PMID 23675474, 2013). "To further determine whether 6 key target genes identified in this study (AKT1, MMP9, ICAM1, TLR4, BCL2, and HIF1A) could be used as therapeutic targets for sepsis and COVID-19, we downloaded the gene expression profiles of sepsis and COVID-19 patients from the GEO database (GSE95233, GSE171110)." (PMID 41411324, 2025). "Thus, the judicious modulation of HIF-1α expression could potentially serve as a therapeutic entry point for enhancing the treatment of sepsis-induced lung injury." (PMID 39712019, 2024). "This process may contribute to the elevated levels of HIF-1α observed in sepsis." (PMID 38539163, 2024). "This might indicate that HIF1α contributes to the decline in PPARα and its signaling in sepsis." (PMID 37006237, 2023). "Therefore, we first investigated whether HIF1α and/or HIF2α expression in the liver contribute to sepsis mortality." (PMID 37006237, 2023).
Sepsis (continued). "During sepsis, HIF-1α, in combination with other driving factors, is responsible for the metabolic switch of immune cells from oxidative phosphorylation to glycolysis, an event known as the Warburg effect, enabling cell proliferation and the cytokine storm described in sepsis." (PMID 37367740, 2023). "However, the molecular mechanisms linking HIF-1α to sepsis-induced diaphragm and mitochondrial injuries remain unknown." (PMID 35163007, 2022). "Moreover, upregulation of HIF-1α after treatment of DMOG cut down the levels of plasma D-lactic acid, DAO, FABP2, and FD-40; while downregualtion of HIF-1α after treatment of BAY 87–2243 aggravated the damage of sepsis to the structure and function of intestinal mucosa." (PMID 35576220, 2022). "In addition, sepsis-AKI patients showed an increased expression of hypoxia-inducible factor 1-alpha (HIF1α), the master oxygen sensor within cells and manganese superoxide dismutase (mnSOD), a key antioxidant enzyme, suggesting an active response to oxidative stress (both p < 0.001)." (PMID 33494815, 2021). "Similarly, HIF-1α deletion in T cells increase survival in a rodent model of sepsis." (PMID 34447792, 2021). "This study further showed that the low HIF-1α expression was dependent on the exposure time to LPS in human monocytes: high HIF-1α expression in the acute administration (likely resembling the early phase of sepsis) and low HIF-1α expression under prolonged stimulation." (PMID 34447792, 2021). "Thus, HIF-1α signaling is intensely involved in the vascular response to sepsis." (PMID 32353952, 2020). "Importantly, HIF1α plays a crucial role in the metabolic switch from oxidative phosphorylation to glycolysis to meet increased energy demands for inflammatory responses during sepsis." (PMID 32479514, 2020). "Thus, myeloid HIF-1α may represent an important link between the immune system, peripheral metabolism, and inflammation in sepsis." (PMID 30524296, 2018). "HIF1α is central to the functional reprogramming of monocytes in sepsis whereby tolerance, tissue remodelling, and antimicrobial responses are controlled, while epigenetic reprogramming dependent on the Akt–mTOR–HIF1α pathway modulates an effective immune response to sepsis in mice." (PMID 26917434, 2016). "Furthermore, we could recently show that leukocyte HIF-1α-mRNA-expression is decreased in severe sepsis and inversely correlated with disease severity." (PMID 27515179, 2016). "Thus, we tested the hypotheses, that SNPs in the HIF-1α or PHD2 genes are common in Caucasians, with 2) the HIF-1α genetic variant being associated with an altered HIF-1α mRNA expression; and 3) independent risk factors for 30-day mortality in severe sepsis." (PMID 27515179, 2016). "In addition, HIF-1α could significantly upregulate TNF-α to progress inflammatory response in the sepsis process formation and alveolar macrophages activated by lipopolysaccharide (LPS)." (PMID 26715469, 2015). "The results showed that, compared with the healthy control group, the expression of EXT1, HIF1A and HMMR was upregulated in sepsis, whereas the expression of CD44, EXT2 and SELL was downregulated in sepsis group." (PMID 40672940, 2025). "In our study, 6 key target genes involved in sepsis and COVID-19 treatment with JHD were identified including AKT1, MMP9, ICAM1, TLR4, BCL2 and HIF1A based on PPI network." (PMID 41411324, 2025). "In sepsis models, UC-MSC-derived exosomes inhibit macrophage glycolysis mediated by HIF-1α, reducing the release of inflammatory factors." (PMID 41488628, 2025). "In the LPS-induced sepsis rat model, cerebral edema and inflammatory cell infiltration were observed, and the expression levels of PI3K, AKT, and HIF-1α were significantly elevated." (PMID 41451413, 2025). "The SphK1/S1PR3 axis promotes glycolysis by upregulating HIF-1α and glycolytic enzymes HK2 and PFKFB3, and it also orchestrates sepsis-induced macrophage polarization into proinflammatory subsets." (PMID 41488672, 2025).
Sepsis (continued). "In the context of sepsis, inflammatory factors such as tumor necrosis factor-α (TNF-α) and interleukin-1β (IL-1β) modulate HIF-1α expression by activating the NF-κB pathway." (PMID 40887582, 2025). "The gene differential expression analysis showed that compared with the healthy group, the sepsis patient group exhibited significantly lower expression levels of AKT1 and BCL2, but significantly higher expression levels of MMP9, ICAM1, TLR4, and HIF1A." (PMID 41411324, 2025). "The Warburg effect and related mediators, such as hypoxia-inducible factor 1-alpha (HIF-1α), are induced in sepsis models, potentially providing cytoprotection and modulating inflammation in response to acute cell stress." (PMID 39585590, 2024). "The expressions of HIF1A and SLC25A37 were significantly higher in the sepsis group compared with that in the control group." (PMID 36937929, 2023). "It has been demonstrated that inhibiting glycolysis contributes to neutrophil immunosuppression during sepsis, regulated by the PI3K/Akt-HIF-1α-pathway-mediated downregulation of lactate dehydrogenase A (LDHA)." (PMID 38001795, 2023). "After normalising the grey values, the expressions of p-PI3K/PI3K, p-AKT/AKT, p-MTOR/MTOR, HIF-1α, and PDK1 were decreased in CLP and LPS-induced sepsis, and the Warburg effector pathway was inhibited." (PMID 37434129, 2023). "The HIF-1α stabilizer BAY-85 and inhibitor BAY-87 were used to explore the role of HIF-1α in PMN glycolysis during sepsis." (PMID 35090526, 2022). "We found LPS-related sepsis visibly upregulated the mRNA expression of IL-6, TNF-α, pyrocytosis-related factors (such as caspase-1), hypoxia-inducible factors (such as HIF1-α), and chemokines." (PMID 35156512, 2022). "Our study here provides unequivocal evidence that Rabeprazole is a HIF-1α inducer, which promotes vascular repair and the resolution of inflammation via endothelial HIF-1α following sepsis challenge." (PMID 35563731, 2022). "Compared with the other three groups, the fluorescence density of HIF-1α was significantly enhanced in sepsis group and the fluorescence density of BNIP3 L was significantly reduced in sepsis group(p < 0.0001)." (PMID 36569834, 2022). "Compared with the sepsis group, the number of expressions of HIF 1a decreased, and BNIP3L expression increased after the administration of HIF-1α inhibitors." (PMID 36569834, 2022). "Using myeloid-specific HIF-1α knockout mice, these authors demonstrated that HIF-1α is a critical protagonist of the sepsis phenotype; HIF-1α promoted the expression of inflammatory cytokines including TNF-α, IL-1, IL-4, IL-6, and IL-12." (PMID 35053299, 2022). "Compared with the control group and the sham group, the number of expressions of HIF-1α increased, and BNIP3L decreased significantly in the sepsis group." (PMID 36569834, 2022). "In genetic depletion of genes encoding for Pink and Park2, a subsequent decrease in neurotransmitter dopamine was accompanied with increase of late sepsis mediator—HMGB1, via mechanism of HIF-1α-dependent anaerobic glycolysis and NLRP3 inflammasome activation." (PMID 34824200, 2021). "We have previously shown that iKIR enhances both STAT-1 and STAT-3 in a murine model of sepsis and that iKIR-mediated STAT-3 activation amplifies HIF1α-mediated glycolysis." (PMID 33690673, 2021). "Indeed, an HIF-1α-dependent miR-210 upregulation in monocytes and macrophages has been observed in response to pathogen interaction in different mouse infection models, and miR-210 inhibition/deletion is beneficial in bacteremia, endotoxemia, sepsis and parasitosis." (PMID 33934122, 2021). "In contrast to NGAL, mnSOD and HIF1α, the expression of SIRT1, involved in inhibiting oxidative stress and the suppression of biogenesis and mitophagy, was downregulated in sepsis-AKI patients." (PMID 33494815, 2021).
Sepsis (continued). "Together with the pro-inflammatory role of PKM2-HIF-1α on LPS-activated macrophages, HIF-1α-mediated immune-metabolic dysfunction was emphasized as a mechanism for lethal sepsis." (PMID 34824200, 2021). "Meanwhile, in the animal study, data presented that administration of Ade-HIF-1α resulted in an increased expression of HIF-1α and STAT3 compared with the sepsis rat model group and the Ade-control group." (PMID 32089644, 2020). "Although the effects of HIF-1α on VILI and sepsis in hypoxemia and sepsis models are already known, the beneficial effects of LMWH in the treatment of sepsis-related lung inflammation through HIF-1α pathway have not been investigated." (PMID 32353952, 2020). "We investigated the relationship between HIF-1α and the CLP-induced sepsis model to analyze the effect of ONB/MPA on HIF-1α downregulation." (PMID 32226527, 2020). "As we had found that the monocytes undergo immunosuppression through the HIF-1α signaling pathway, the further study of FCM analysis identified that PD-L1 expressed on the monocytes was higher in the late phase of sepsis compared with the early phase." (PMID 32089644, 2020). "HIF-1α deletion in myeloid cells led to reduced proinflammatory cytokines such as IL-1, IL-12, and TNF-α in the rat model of sepsis." (PMID 31093315, 2019). "In a mouse model of LPS-induced Sepsis, HIF-1α induced a proinflammatory phenotype in monocytes and deletion of HIF-1α led to improved survival." (PMID 30804946, 2019). "With the aggravating condition of sepsis, on the one hand, the HIF = 1 target gene expression was decreased; on the other hand, the HIF-1α mRNA expression was decreased." (PMID 31781604, 2019). "In this sepsis model, macrophage metabolic reprogramming is dependent on the STAT3/HIF1α/glycolysis axis and inhibition of glycolysis ameliorates susceptibility to sepsis." (PMID 30249998, 2018). "In this section, we will explore signaling pathways involved in the inflammatory response during sepsis, with a particular focus on the MAPK, hypoxia-inducible factor 1α (HIF-1α), and nuclear factor-erythroid 2-related factor 2/Kelch-like ECH-associated protein 1 (Nrf2/Keap1) pathways." (PMID 41041277, 2025). "Understanding these mechanisms provides valuable insights into potential therapeutic targets, such as HIF-1α and VEGF inhibitors, which could disrupt this cycle and improve outcomes for patients with sepsis and cancer." (PMID 40563999, 2025). "The upregulation of HIF-1α can be demonstrated efficacy in ameliorating symptoms of ARDS and sepsis through mechanisms, such as attenuating inflammatory factor expression, reducing oxidative stress, facilitating metabolic reprogramming, and modulating mitochondrial biogenesis." (PMID 40887582, 2025). "In a mouse model of sepsis, inhibition of LDHA expression by regulating PI3K/Akt-HIF-1α pathway could inhibit glycolysis and contribute to immunosuppression of neutrophils." (PMID 40420943, 2025). "Accordingly, we found that sepsis alters chromatin accessibility with enrichment of AP-1 motifs and enhanced JAK-STAT, HIF-1α and TLR signaling - which are established mechanisms of immune memory - in association with an enhanced lung injury phenotype that persists for at least 3 months." (PMID 40475424, 2025). "In LPS-induced sepsis rat model, PF pretreatment inhibited PI3K/Akt/ERK-mediated HIF-1α and TLR4/MyD88/NF-κB signaling, thereby reducing inflammation by decreasing the levels of tumor necrosis factor-α (TNF-α) and interleukin-1β (IL-1β) in serum and cardiac tissue." (PMID 41311552, 2025). "In addition, our study has revealed a CD38‐NAD+‐HIF‐1α/glycolysis/MGO positive feedback loop that exacerbates monocytes activation and dysfunction in sepsis." (PMID 40145840, 2025). "Collectively, these results provided evidence of our hypothesis that the CD38‐NAD+‐HIF1‐α/glycolysis/MGO loop promoted the activation of monocytes and therefore exacerbated sepsis‐induced immune dysfunction." (PMID 40145840, 2025).
Sepsis (continued). "Additionally, in sepsis-induced acute lung injury mice, overexpression of histone methyltransferase (SETD2) inhibits HIF-1α, thereby reducing M1 macrophage polarization and glycolysis." (PMID 39712019, 2024). "Additionally, SENP3 can enhance M1 macrophage polarization and the production of pro-inflammatory cytokines through the HIF-1α/PKM2 axis, contributing to sepsis-induced lung injury." (PMID 39712019, 2024). "Focusing on hub genes (putative driver transcription factors), they identified the HIF-1 transcription factor complex (HIF1α and ARNT [HIF1β]), which is involved in immune cell metabolism, coagulation, proliferation, apoptosis, and, ultimately, sepsis survival." (PMID 38991496, 2024). "In addition, the study found that silencing of miR-31 protected against intestinal barrier dysfunction by inhibiting the NF-κB/HIF-1α pathway and targeting HMOX1 during sepsis." (PMID 38187112, 2023). "Therapeutic activation of HIF-1α signaling and HIF-1α/FoxM1-dependent vascular repair therefore represents a putative therapeutic strategy for the treatment of inflammatory vascular diseases, such as sepsis and ARDS." (PMID 35563731, 2022). "The inhibition of glycolysis contributed to neutrophil immunosuppression during sepsis and might be controlled by PI3K/Akt-HIF-1α pathway-mediated LDHA downregulation." (PMID 35090526, 2022). "HIF-1α was shown to be a critical determinant of sepsis promoting the production of inflammatory cytokines, including TNF-α, IL-1, IL-4, IL-6, and IL-12, which reach harmful levels during early sepsis." (PMID 35682644, 2022). "It has been proved that downregulating the activated HIF-1α, the HDAC4 client transcription factor, could improve the prognosis of sepsis and relieve myocardial injury during sepsis." (PMID 35091534, 2022). "Our study demonstrated that the inhibition of glycolysis contributed to neutrophil immunosuppression during sepsis and might be controlled by PI3K/Akt-HIF-1α pathway-mediated LDHA downregulation." (PMID 35090526, 2022). "Regarding to the transcription factors AP1 and HIF-1α, sepsis did not change their expression in brain of mice." (PMID 33608025, 2021). "Interestingly, with the coimmunoprecipitation assay, results showed that proteins HIF-1α and STAT3 coregulated at the transcriptional level in the immune process of sepsis." (PMID 32089644, 2020). "Additionally, the proteins HIF-1α and STAT3 were coregulated at transcriptional levels during the inflammatory responses of sepsis." (PMID 32089644, 2020). "Moreover, in the clinical study, the programmed cell death-ligand 1 (PD-L1) was overexpressed in monocytes in the late phase of sepsis, while the expression of proteins HIF-1α and STAT3 was decreased in the late phase of sepsis." (PMID 32089644, 2020). "Another transcription factor, hypoxia-inducible factor-1α (HIF-1α) is induced by Gram-negative endotoxin challenge in mice and upregulated in sepsis-monocytes." (PMID 33382782, 2020). "Taken together, our results accord with the previous findings that inhibition of HIF-1α activity could be a novel therapeutic target for the treatment of ALI and sepsis in animal studies and human shock states." (PMID 32353952, 2020). "Additionally, in the clinical study, the western blot analysis of the proteins HIF-1α and STAT3 showed that the expression of protein STAT3 was significantly reduced in the late phase of sepsis compared with the primary phase." (PMID 32089644, 2020). "Given that hypoxia-inducible factor (HIF)-1α has been described as an important factor for the metabolic reprogramming of myeloid cells during sepsis, we next analyzed how P2X7 receptors could be controlling HIF-1α." (PMID 31221993, 2019). "Additionally, pharmacological inhibition of HIF-1α using 2-Methoxyestradiol, protected mice from LPS and CLP induced sepsis." (PMID 31555665, 2019).